SOCS3 (suppressor of cytokine signaling 3)
Diseases named in the same sentence as SOCS3 in open-access papers (continued):
Sharing a sentence is not in itself a finding about the gene and the disease.
Obesity (continued). "Socs3 mRNA levels in the arcuate are increased after prolonged high fat diet exposure, while Socs3 deficiency or specific deletion of Socs3 in POMC neurons leads to enhanced leptin sensitivity and resistance to diet induced obesity." (PMID 33382813, 2020). "SOCS3 is also a leptin resistance inducer, thus leads to increased lipogenesis, obesity and hepatic steatosis." (PMID 32158492, 2020). "Most individuals with obesity have leptin resistance by leptin and its receptor inhibitor SOCS-3 (suppressor of cytokine signaling-3), leading to dysfunction of leptin biological function." (PMID 33071815, 2020). "Suppressor of cytokine signaling 3 (SOCS3) is another molecule responsible for hypothalamic insulin signaling induced by obesity." (PMID 30875909, 2019). "Socs3, a negative regulator of leptin receptor signaling, can inhibit fatty acid oxidation and mediate leptin resistance and diet-induced obesity." (PMID 31333621, 2019). "As it is influenced by inflammation, the reduction in the levels of SOCS3 has been reported to be a protective factor that acts to prevent obesity-induced insulin sensitivity." (PMID 31060494, 2019). "Impaired transport across the BBB, endoplasmic reticulum (ER) stress, obesity-induced chronic inflammation, and hyperleptinemia-induced suppressor of cytokine signaling 3 (SOCS3) transactivation are regarded as factors of leptin resistance." (PMID 31408957, 2019). "The role of SOCS3 in obesity was strongly supported by our pathway enrichment analysis and the differential gene expression in the metabolic tissues." (PMID 30619480, 2018). "The relevance of NPY and its role, in combination with other regulatory peptides (POMC, AgRP, MC4-R and SOCS3), was clearly seen in adulthood, when obesity was settled in L-females." (PMID 29329236, 2018). "Future studies are warranted to discover more potential drug targets using larger sample sizes from metabolic tissues, and to elucidate the mechanism of SOCS3 DNA methylation interacting with obesity." (PMID 30619480, 2018). "Note, liver-specific suppressor of cytokine signaling-3 deletion in mice enhanced hepatic insulin sensitivity but increased lipogenesis to result in fatty liver disease and obesity." (PMID 30547786, 2018). "The expression of the suppressor of cytokine signaling 3 (SOCS3) gene, which plays an important role in the pathogenesis of obesity in animal models, was downregulated (P < 0.05)." (PMID 29121861, 2017). "This supports the harmful role of leptin and meaningful regulator role of SOCS-3 in obesity-related OA." (PMID 27716333, 2016). "In cases of obesity, SOCS3 is upregulated in skeletal muscles, the liver, in adipose tissues and in the hypothalamus, and this upregulation is associated with increased inflammation." (PMID 27337171, 2016). "Based on these evidences, molecules that intervene SOCS3 actions would represent a potential therapeutic target in the treatment of obesity and type 2 diabetes." (PMID 27812350, 2016). "SOCS-3 is a leptin-inducible inhibitor of leptin signalling and a potential mediator of leptin resistance in obesity." (PMID 27479001, 2016). "Overall this study demonstrates that early-onset obesity as a result of maternal HFD during lactation does not only dysregulate intrinsic-pulmonary STAT3-AMPKα-SOCS3, but also activate AKT/GSK3β pathway, indicative for insulin signaling." (PMID 27087690, 2016). "Previous research has established that changes in the expression of SOCS3, leptin, and the activation of STAT3, and AMPK are linked to the regulation of insulin signaling in obesity and diabetes." (PMID 24997069, 2014). "Leptin levels are increased and its negative regulators, SOCS-3 and sOb-R are decreased in obese patients with osteoarthritis: a link between obesity and osteoarthritis." (PMID 25184806, 2014). "HFD-induced obesity in mice increases hyperleptinemia and hypothalamic leptin resistance through induction of suppressor of cytokine signaling (SOCS)-3." (PMID 23696840, 2013).
Obesity (continued). "We propose that any mechanism that increases SOCS3 protein expression beyond a certain level in POMC neurons will cause long-term leptin resistance in those cells and eventually to obesity." (PMID 22276206, 2012). "Here, we demonstrate that SOCS3 mRNA expression is increased in murine skeletal muscle in the setting of diet-induced and genetic obesity, inflammation, and hyperlipidemia." (PMID 23115649, 2012). "Suppressor of cytokine signaling 3 (SOCS3) is a major negative regulator of both leptin and insulin signaling, thereby implicating SOCS3 in the pathogenesis of obesity and associated metabolic abnormalities." (PMID 23115649, 2012). "Taken together, regulation of the IL-6/STAT3/SOCS3 pathway in muscle cells seems to change with obesity, possibly due to alterations in circulating cytokine levels and composition." (PMID 22761857, 2012). "SOCS3 is a negative regulator of leptin signaling and was recently proposed as an important therapeutic target for obesity." (PMID 22871059, 2012). "In conclusion, our data do not suggest evidence for a major role of the respective SNPs in SOCS3 in the pathogenesis of extreme obesity in our study groups." (PMID 17445271, 2007). "We investigated association of variations in the coding sequence and promoter region of SOCS3 with extreme obesity in German children and adolescents." (PMID 17445271, 2007). "SOCS3 is also known to be upregulated in the hypothalamus by diet-induced obesity." (PMID 40690443, 2025). "However, elevated leptin levels in obesity increased SOCS3 expression, which in turn inhibits JAK2–STAT3 activation and further reduces leptin signaling and sensitivity." (PMID 41516046, 2025). "This aligns with the established understanding of chronic inflammation associated with obesity, where SOCS3 acts as a negative feedback regulator to modulate inflammatory responses." (PMID 40191199, 2025). "Notably, SOCS1 and SOCS3 dysregulation intersect with host comorbidities such as obesity, type 2 diabetes, and metabolic syndrome, all of which are strongly associated with increased COVID‐19 severity and mortality." (PMID 40844207, 2025). "It is noteworthy that SOCS3 expression is elevated in obesity." (PMID 39596321, 2024). "The development of drugs that inhibit SOCS3 activity or expression may, therefore, represent a potential strategy for treating type 2 diabetes, obesity, and other metabolic disorders." (PMID 39596321, 2024). "Interestingly, SOCS3 photoperiod-related expression changes suggest that it is altered not only during obesity, but also according to seasonality, therefore contributing to the peculiar feeding behavior." (PMID 36674520, 2023). "Hypothalamic Slug–elicited epigenetic reprogramming may act in concert with Sh2b1, SOCS3, PTP1b, and additional regulators to promote leptin resistance and obesity." (PMID 36512408, 2023). "Moreover, inhibiting SOCS3 production in adipose tissue of female mice can ameliorate whole-body insulin sensitivity in obesity." (PMID 36609306, 2023). "Therefore, excessive SOCS3 activity is considered as a potential mechanism for the leptin resistance that characterizes human obesity." (PMID 36978976, 2023). "Furthermore, PEA reduced SOCS3 protein expression whose increase is involved in leptin resistance and obesity." (PMID 35214069, 2022). "Moreover, and possibly in connection with the key role of SOCS3 and PTP1B in leptin action, endoplasmic reticulum (ER) stress has also been identified as a mechanism implicated in the development of obesity-associated leptin resistance." (PMID 34523036, 2022). "Previous evidence suggested that the suppressor of cytokine signaling 3 (SOCS3) played an essential role in the regulation of energy metabolism homeostasis, which inhibited the activity of insulin and leptin (characteristic feature in human obesity)." (PMID 36145200, 2022).
Obesity (continued). "Several studies have estimated the relationship between SOCS3 methylation and obesity; however, considering the cross-sectional nature of those traditional observational studies, they could not determine the causal effect between risk factors and disease." (PMID 36145200, 2022). "Moreover, when the body is suffering from metabolic abnormalities, such as obesity, SOCS3 is involved in the inhibition of inflammatory cytokines and crucial hormones linked to energy metabolism, such as insulin signaling and leptin." (PMID 36145200, 2022). "Knockdown of SOCS3 in obese mice offset the protection against VILI afforded by obesity." (PMID 34489970, 2021). "Therefore, the protective effect of obesity against VILI was significantly offset after SOCS3 attenuation." (PMID 34489970, 2021). "In answering these questions we may be able to identify further critical regulators of the inflammatory response (e.g., SOCS3) that are dysregulated in obesity and other co-morbidities." (PMID 34777390, 2021). "Elevated SOCS3 in obesity, because of meta-inflammation, may therefore blunt the anti-viral IFN response, rendering obese patients more susceptible to IAV or SARS-CoV-2 infection." (PMID 34777390, 2021). "Moreover, hypomethylation of SOCS3 associated with T2DM risk and mediated the effect of important environmental factors such as obesity, sedentary time and stress." (PMID 34001206, 2021). "In the occurrence and development of obesity-related OA, SOCS3 may be a key factor in the regulation of TLR4 signaling by leptin." (PMID 34457118, 2021). "SOCS3 played an important role in obesity attenuated VILI in our study." (PMID 34489970, 2021). "Conversely, arcuate-specific or POMC neuron-specific overexpression of Socs3 leads to obesity." (PMID 33382813, 2020). "Obesity promotes SOCS3 expression in the hypothalamus, adipose tissue, liver, and skeletal muscle, and SOCS3 might also upregulate the expressions of adipocyte inflammatory cytokines like IL-6, TNF-α, and MCP-1." (PMID 32215011, 2020). "Increased leptin levels in obesity may promote infection by lowering anti-viral type 1 IFN through the activation of suppressor of cytokine signaling-3 (SOCS-3) expression." (PMID 33123087, 2020). "Mice with SOCS3 deletion either in the whole brain or in proopiomelanocortin (POMC) neurons (the key leptin target neurons in the arcuate nucleus of the hypothalamus) are resistant to high-fat diet-induced obesity." (PMID 31141984, 2019). "In addition, this study is one of the first to investigate gene–gene and gene–environment interactions between NFKB1, IKBKB, SOCS3 and macronutrient intakes on human and their effect on obesity-related phenotypes." (PMID 30886629, 2019). "While Socs3 levels may increase as a result of obesity in these animals, this increase appears to be graded, with nonobese AAV-Cre animals showing a trend for increased hypothalamic Socs3 expression (log2 FC = 1.2)." (PMID 29376887, 2018). "Targeting SOCS-3 expression and PTPs activity using appropriate inhibitors and implying ER stress reducing measures could help in reversing leptin insensitivity in obesity." (PMID 29868503, 2018). "Of note, inflammatory genes, including NFκB and SOCS3, were downregulated in hypothalamus after long-term EE, which could contribute to the EE’s anti-obesity phenotype." (PMID 30036185, 2018). "Among the genes affiliated with the 119 significant CpGs, SOCS3 and DOK2 were differentially expressed in the SAT of obesity patients, while seven genes (SOCS3, PRR5L, ABCG1, BRDT, B3GNT7, ZNF710, and RARRES1) were differentially expressed in the VAT of obesity patients." (PMID 30619480, 2018). "Besides beneficial effects, chronic activation of STAT3 in obesity leads to constant expression of its own inhibitor, SOCS3, disrupting the homeostasis of the IL-6 signaling pathway." (PMID 30591653, 2018).
Obesity (continued). "Likewise, mice overexpressing a constitutively active version of STAT3 in POMC neurons show elevated SOCS3 expression and develop obesity as a result of hyperphagia and decreased POMC expression accompanied by central leptin resistance." (PMID 28270795, 2017). "Also, showed an increase of the suppressor of the cytokine signaling proteins including SOCS3 in the liver, muscle, and fat, in obesity." (PMID 26823690, 2016). "In the present study leptin was positively associated and SOCS-3 was negatively associated with MMP levels in SF in obese but not in non-obese patients with OA, further confirming the importance of the leptin-SOCS-3 axis in cartilage metabolism and its possible significance in obesity-induced OA." (PMID 27716333, 2016). "SOCS3 expression in the CNS is largely increased in obesity." (PMID 24600449, 2014). "SOCS3 overexpression in the hypothalamus induces leptin resistance and obesity, while its inactivation in the hypothalamus has been shown to enhance the response to endogenous satiety signals and attenuate obesity in mice fed a high-fat diet." (PMID 23967267, 2013). "Consistent with this “SOCS3-threshold” hypothesis, it was recently demonstrated that genetically-driven over-expression of SOCS3 in POMC neurons is sufficient to cause obesity even in chow-fed mice." (PMID 22276206, 2012). "We propose a model where chronic over-stimulation of the leptin-LepRb signaling pathway in arcuate neurons may play a role in development of arcuate leptin resistance and diet-induced obesity, possibly via elevation of SOCS3 expression." (PMID 22276206, 2012). "(iii) Several rodent models of leptin resistant obesity exhibit increased Socs3 expression." (PMID 17445271, 2007). "The lack of association between the SOCS3 SNPs and obesity is probably because they are not in LD with a functional site." (PMID 17445271, 2007). "It is worth noting that, beyond SOCS3 and PTP1B, several additional molecules and cellular mechanisms have been implicated as negative regulators of LepRb signaling and may contribute to the development of leptin resistance in obesity." (PMID 41251447, 2025). "Thus, SOCS3 may contribute to the development of diet-induced obesity and hypothalamic leptin resistance." (PMID 40690443, 2025). "Moreover, network construction produced similar results: Rumonococcus, Lachnospiraceae_NK4A136-group, Prevotellaceae_NK3B31_group, and Clostridium_sensu_stricto_1 were involved in the accumulation of IL-1β, TNF-α, MG,AGEs, TG, AgRP, and SOCS3 for the development of obesity." (PMID 38659208, 2024). "This suggests that obesity caused by caponization is closely related to LEP resistance, similar to a previous finding that exogenously administered LEP did not induce a signal transducer and activator of transcription 3 (STAT3) phosphorylation and or increase SOCS3." (PMID 39201373, 2024). "Hence, it can be speculated that increased expression of SOCS3 in adipose tissue from individuals with obesity can lead to metabolic abnormalities pertinent to obesity." (PMID 36609306, 2023). "Furthermore, obesity-related inflammation leads to the upregulation of SOCS3 proteins in several tissues, leading to the inhibition of insulin signaling and, therefore, representing an interesting mechanism connecting the immune and metabolic system in a delicate and balanced cross-talk." (PMID 35631263, 2022). "Furthermore, therapies designed to suppress SOCS3 in skeletal muscle might be effective in reversing obesity-related glucose intolerance and IR." (PMID 34565450, 2021). "Therefore, this study was designed to test our hypothesis that obesity and SOCS3 contribute to the attenuation of inflammation and the enhancement of AFC in an obese VILI mouse model." (PMID 34489970, 2021). "Therefore, the potential therapeutic strategy for obesity-related OA could be by inhibiting the leptin signal via the reduction of leptin levels and enhancement of SOCS3 expression, or by directly suppressing TLR4 expression." (PMID 34457118, 2021).
Obesity (continued). "Therefore, hyperleptinemia and hypothalamic inflammation in diet-induced obesity may activate a common negative regulator of leptin signaling, SOCS3 or PTP1B, and contribute to central leptin resistance." (PMID 32630697, 2020). "Therefore, in obesity the potential failure of vaccination, especially against viral infections could be regulated by SOCS3 antagonists." (PMID 29868503, 2018). "For SOCS3, CISH, PIM3 (Pim-3 proto-oncogene, serine/threonine kinase), and KLF4 (Kruppel-like factor 4), obesity was associated with decreased methylation and increased gene expression, while for HRASLS2, obesity was associated with decreased methylation and decreased gene expression." (PMID 29312471, 2018). "SOCS3 may serve as a target for drug development of obesity and its complications." (PMID 30619480, 2018). "Thus, elevated hepatic SOCS3 levels in obesity impair both insulin and IL-6 signaling, thereby inducing a vicious cycle that might ultimately lead to cancer." (PMID 30591653, 2018). "Chronic inflammation in obesity contributes to this condition, as TNF-α and the suppressor of cytokine signaling 3 (SOCS3) pathways impair leptin signaling in the hypothalamus." (PMID 40862455, 2025). "When SOCS3 is overexpressed in POMC neurons, it triggers a cascade of physiological responses that culminate in hyperphagia and the development of obesity." (PMID 40283443, 2025). "Mechanistically, this signaling can down-regulate JAK2-STAT3 through the binding of the SH2 domain of suppressor of cytokine signaling 3 (SOCS3) to LepRb Tyr985, contributing to leptin’s anti-obesity effects." (PMID 41251447, 2025). "Overall, the persistence of pSTAT3 in the anti-mesometrial area of HFD mice uteri suggests a potential role for SOCS3 and PTPN2 in mediating obesity-induced changes in decidual function." (PMID 39090270, 2024). "Mechanistically, reticuline inactivated the JAK2/STAT3/SOCS3 and p38 MAPK/NF‐κB signaling pathways in obesity‐related asthma." (PMID 38286741, 2024). "Semaglutide treatment restored GLP-1 levels, regulated Socs3 expression in ARC and improved leptin sensitivity and the hypothalamic anorexigenic signaling (POMC/MC4R) for obesity control in these obese mice." (PMID 39728000, 2024). "Ueki demonstrated in a mouse model that in both obesity and lipopolysaccharide (LPS)-induced endotoxemia there is an increase in SOCS proteins, SOCS1 and SOCS3, in the liver." (PMID 37511764, 2023). "SOCS3 is an inhibitor of STAT3, an important marker of leptin signaling as deletion of the STAT3 gene in the CNS induces obesity." (PMID 37571301, 2023). "The up regulation of SOCS3 in POMC neurons leads to the damage of STAT3 signal, resulting in leptin resistance and obesity." (PMID 36615730, 2022). "Leptin is chronically produced by AT in individuals with obesity and interferes with IFN signaling by increasing Suppressor of Cytokine Signaling 3 (SOCS3)." (PMID 36466818, 2022). "The increase of SOCS3 expression leads to the down-regulation of JAK2 pathway and the impairment of STAT3 signal, leading to leptin resistance, obesity and abnormal glucose metabolism." (PMID 36615730, 2022). "Nevertheless, the interaction between SOCS3 and WNK4 in modulating VILI in obesity warrants further investigation." (PMID 34489970, 2021). "SOCS3 is a key regulator of IFN-I as well as of leptin and pro-inflammatory cytokines, which are elevated in obesity." (PMID 33430520, 2021). "Simultaneously, POCU1b inhibited the development of obesity-induced IR via AMPK activation, and the inhibition of NF-κB DNA-binding activity and SOCS-3 overexpression." (PMID 33255404, 2020). "In fact, up-regulation of SOCS3 in proopiomelanocortin (POMC) neurons leads to impairment of STAT3 signaling, with consequential leptin resistance and obesity, as well as glucose intolerance." (PMID 32630697, 2020). "In obesity, increased AT IL6, IL6R, and SOCS3 mRNA expression was observed, however, unchanged AT IL6, IL6R and IL6ST expression was also reported." (PMID 29737494, 2018).